ITGB1 (integrin subunit beta 1)
Diseases named in the same sentence as ITGB1 in open-access papers (continued):
Sharing a sentence is not in itself a finding about the gene and the disease.
asthma (3 papers, 2011 to 2020). "Available reports also suggest that Itgb1 may be involved in the airway smooth muscle responsiveness through the association with fibronectin and type I collagen during asthma or allergic inflammation." (PMID 21211037, 2011).
bladder tumor (3 papers, 2023 to 2025). "The tissue chips from 181 BLCA patients with T1‐stage who underwent transurethral resection of bladder tumor (TURBt) were utilized to analyze the expression profile and clinical significance of the Piezo1/ITGB1 axis." (PMID 40667648, 2025).
brain tumor (3 papers, 2015 to 2021). "Among all subtypes of brain tumors, the clinical data-mining analysis also indicated that ITGA2 and ITGB1 expression levels were significantly higher in GBM than other subtypes of brain tumors." (PMID 34120610, 2021).
clear cell renal cell carcinoma (3 papers, 2020 to 2024). "The effect of LOXL2 on upregulating ITGB1 expression via inhibiting degradation of ITGB1 protein by proteasome pathway has been reported in clear cell renal cell carcinoma, however the authors did not do any further studies to investigate the interactions of the two proteins." (PMID 38326908, 2024).
colitis (3 papers, 2013 to 2023). Inflammation of the colon. "Interestingly, SMAD7 is overexpressed in the inflamed mucosa of IBD patients and targeting of SMAD7 has shown efficacy in mouse models of colitis, while ITGB1 single nucleotide polymorphisms have been identified as a risk factor in IBD." (PMID 24062740, 2013). "We found that the expression of ITGA6 (integrin α6) and ITGB1 (integrin β1), which bind to TK peptides (CT), was significantly increased in the colon of mice with acute colitis." (PMID 36552583, 2022). "In TNBS models of colitis, mucosal ITGB1 expression correlated directly with disease severity, revealing a correlation between mucosal hypoxia and ITGB1 expression in vivo." (PMID 24062740, 2013).
diabetic retinopathy (3 papers, 2024 to 2025). "The clinical progression of intracerebral hemorrhage (ICH) is also associated with the expression of ITGB1; ITGB1 was also significantly downregulated in the retinal tissues of mice with diabetic retinopathy (DR) model." (PMID 38279122, 2024). "Furthermore, it was indicated that unstable ITGB1 mRNA could inhibit inflammation and neovascularization to prevent the progression of diabetic retinopathy (a main complication of DM) in a mouse model." (PMID 38204223, 2025).
emphysema (3 papers, 2012 to 2023). "ITGB1 gene expression was also down-regulated with increasing emphysema severity in lung tissue (P = 0.008)." (PMID 22937864, 2012). "In ITGB1-kickout mice, genetic deletion of monocyte chemoattractant protein-1 receptor impairs the recruitment of monocyte-derived macrophages, which can accelerate the progression of inflammation and severely pre-matures the destruction of emphysema." (PMID 37941009, 2023).
hypertrophic cardiomyopathy (3 papers, 2021 to 2025). A condition in which the myocardium is hypertrophied without an obvious cause. "H0UWL7/ACE and H0VDM6/ITGB1 have been recognized in hypertrophic cardiomyopathy disease pathways." (PMID 34466782, 2021). "Changes in AS of ATP5C1, DCLK2, and MAP3K4 rewire interactions with a “Hypertrophic cardiomyopathy” pathway, and of CACNA1C, TPM3, and ITGB1 rewire interactions with the “Diabetic cardiomyopathy” pathway." (PMID 40337913, 2025).
laryngeal squamous cell carcinoma (3 papers, 2021 to 2025). A squamous cell carcinoma that arises from the larynx. "Another study showed that miR-139-3p is significantly downregulated in laryngeal squamous cell carcinoma and that its expression regulates several cancer-related genes, (e.g., RAB5A, ITGB1, FAK, PXN, VEGF, and MMP9)." (PMID 34576110, 2021). "Similar findings have been reported in laryngeal squamous cell carcinomas for other binomial LncRNA/mRNA transcripts, such as: NR_003919/PIK3R1, NR_027340/ITGB1, MIR31HG/HIF1A, and SOX2‐OT/DDIT4." (PMID 33433063, 2021).
lung disease (3 papers, 2021 to 2023). "In our study, this pathway was significantly extracted from general SSc (upregulated proteins) and lung disease related to SSc (downregulated proteins) subgroups (ITGB1;ACTN1;ICAM1;ITGAM;MMP9)." (PMID 36732374, 2023).
meningioma (3 papers, 2022 to 2025). A generally slow growing tumor attached to the dura mater. "Interaction with tissue stem cells through the Itgb1/Vcam1 pathway may reflect the complex role of T cells in regulating the meningioma tumour microenvironment, promoting immune responses and inhibiting or promoting tumour growth." (PMID 40046334, 2025). "The in silico pathway analysis was followed by validation of integrin-linked kinase (ILK) along with its associated pathway components, like ITGB1 and VIM, which are known to play important roles in regulating the EMO and EMT transmission responsible for the progression of meningioma." (PMID 37887327, 2023). "The peak areas of peptides ITGB1 and ILK showed upregulation in high-grade meningioma when compared with control samples and low-grade meningioma." (PMID 37887327, 2023).
myocardial infarction (3 papers, 2022 to 2023). Gross necrosis of the myocardium, as a result of interruption of the blood supply to the area, as in coronary thrombosis. "Extracellular vesicle-derived circular ITGB1 can exacerbate heart damage and inflammation, which can cause acute myocardial infarction." (PMID 37941009, 2023). "ITGB1 upregulation is capable of increasing cardiac function and clinical outcome after myocardial infarction." (PMID 36248430, 2022).
osteoarthritis (3 papers, 2023). A noninflammatory degenerative joint disease occurring chiefly in older persons, characterized by degeneration of the articular cartilage, hypertrophy of bone at the margins and changes in the synovial membrane. "Interestingly, ITGAV, ITGB1, and ITGA10 involve multiple chondrocyte subtypes, which suggests that they have a greater impact on the development of osteoarthritis." (PMID 37660146, 2023).
renal fibrosis (3 papers, 2020 to 2025). A final common manifestation of a wide variety of chronic kidney diseases characterized by glomerulosclerosis and tubulointerstitial fibrosis. "ITGB1, considered a marker of renal fibrosis, can be targeted with miR‐124‐3p to reverse fibrosis progression, and its inhibition has shown potential in mitigating silicosis severity in mice." (PMID 40165483, 2025).
sarcoma (3 papers, 2013 to 2024). A usually aggressive malignant neoplasm of the soft tissue or bone. "U-2 OS is a sarcoma cell line in which immunofluorescence (IF) staining of ITGB1 is mainly distributed in the cytoplasm, especially in the perinuclear area." (PMID 38814534, 2024). "Likewise, ECM‐triggered ITGB1 signalling, including the addition of exogenous laminin (from Engelbreth–Holm–Swarm murine sarcoma basement membrane), promoted the formation and adhesion of OC spheroids." (PMID 36647260, 2023).
Sepsis (3 papers, 2020 to 2025). Sepsis is defined as life-threatening organ dysfunction caused by a dysregulated host response to infection. "In line with Ilk1 and Fermt2, genes encoding for the integrin subunits (Itga7 and ItgB1) were upregulated (more than 2-fold; P < 0.001 versus healthy control mice) after five days of sepsis." (PMID 41385533, 2025). "Similar to the TA, gene expression of Itga7, ItgB1, Tln1, Vcl1 and Parvb was upregulated in sepsis." (PMID 41385533, 2025). "In rAAV-sh-controls, sepsis induced upregulation across TA and EDL muscle of Ilk1 and Fermt2 and integrin-receptor-complex-related genes Itga7, ItgB1, Tln1, Lims1, Lims2, Parva (P < 0.001), whereas in SOL muscle Lims1, Lims2 and Fermt2 were not and Vcl1 (P < 0.001) was upregulated." (PMID 41385533, 2025).
squamous cell carcinoma (3 papers, 2016 to 2023). A carcinoma arising from squamous epithelial cells. "For the human squamous cell carcinoma data, ITGB1 (integrin subunit beta 1) was specifically distributed in the boundary region between the tumor and stromal area." (PMID 36243975, 2023). "In a human clinical trial of PD-1 checkpoint inhibitor treatment of two types of squamous cell carcinoma, high expression of TSK-specific genes ITGB1 and PLAU correlated with significantly reduced progression-free survival (p = 0.0137)." (PMID 32579974, 2020).
acute respiratory distress syndrome (2 papers, 2019 to 2025). Progressive and life-threatening pulmonary distress in the absence of an underlying pulmonary condition, usually following major trauma or surgery. "Although ITGB1 on alveolar epithelium was found to alleviate epithelial injury and remodeling in acute respiratory distress syndrome, profiles and functions of ITGB1 and their family members in lung TCs remain unclear due to the limited source of preliminary lung TCs." (PMID 31888636, 2019). "In the context of lung fibrosis, for example, investigating the role of ITGB1 and TGFβ-1 in the development of VILI and acute respiratory distress syndrome (ARDS) could provide valuable insights into how mechanical stress leads to fibrotic changes in lung tissue." (PMID 41154695, 2025).
arrhythmogenic right ventricular cardiomyopathy (2 papers, 2023 to 2025). "Itgb1 deficiency increases the risk of ventricular arrhythmias in patients with arrhythmogenic right ventricular cardiomyopathy." (PMID 37010266, 2023).
astrocytoma (2 papers, 2013 to 2020). "Our results indicate that alterations of SGCG, PROS1 and ITGB1 genes appeared prevalently in grade III astrocytomas and resulted in shorter survival of patients, implying more aggressive nature of tumors with this genetic signature." (PMID 24358143, 2013).
autoimmune disease (2 papers, 2007 to 2024). A disorder resulting from loss of function or tissue destruction of an organ or multiple organs, arising from humoral or cellular immune responses of the individual to their own tissue constituents. "Pro-inflammatory cytokines, such as TNF or IL12A, the T-cell activation molecule CD28, the regulatory molecules IL10, TGFB1 or the adhesion molecules ITGA4 and ITGB1 have all been evaluated previously as therapeutic targets for autoimmune diseases, including MS." (PMID 18030350, 2007).
benign prostate hyperplasia (2 papers, 2013 to 2024). "More importantly, as a proof of concept, we have identified the proteins ITGA3 and ITGB1 to be significantly more abundant in urine of mPCa compared to benign prostate hyperplasia (BPH) and PCa patients." (PMID 24371517, 2013). "Finally, ITGA3 and ITGB1 were more abundant in urine exosomes of metastatic patients (p<0.05), compared to benign prostate hyperplasia or PCa." (PMID 24371517, 2013).
chronic kidney disease (2 papers, 2018 to 2020). Impairment of the renal function secondary to chronic kidney damage persisting for three or more months. "For instance, inhibition of ITGB1 hinders tPA-mediated fibroblast proliferation in chronic kidney diseases." (PMID 33299380, 2020). "In this setting, the specific role of Itgb1 in water reabsorption homeostasis can be only inferred since the progressive development of chronic renal failure could impair water reabsorption along the distal nephron." (PMID 30271355, 2018).
Crohn disease (2 papers, 2022 to 2025). A gastrointestinal disorder characterized by chronic inflammation involving all layers of the intestinal wall, noncaseating granulomas affecting the intestinal wall and regional lymph nodes, and transmural fibrosis. "Natalizumab, used in multiple sclerosis and Crohn’s disease, has the potential to be repurposed against ITGB1 dysregulation." (PMID 36293493, 2022).
cyst (2 papers, 2018 to 2024). A sac-like closed membranous structure that may be empty or contain fluid or amorphous material. "As a result, Lu+ BC acquired cyst formation capacity by the activation of Itgb1." (PMID 30059007, 2018). "Although the inhibition of Itgb1 signaling did not affect the expression of Lu, it dramatically changed Lu- BC to Lu+ BC-like phenotype in both scratch assay and cyst formation assay." (PMID 30059007, 2018). "While PC-loss-induced ITGB1 activation may not be a prerequisite for initial RhoA activation/MRTF induction, sustained ITGB1 activation/expression (promoted by increased cell contractility, stretching of the cyst wall, or ECM stiffening) may signify a potent feed-forward mechanism." (PMID 38891116, 2024).
dermatitis (2 papers, 2017). An inflammatory process affecting the skin. "Given that SHARPIN indeed inhibits integrin activity in mouse epidermis, we hypothesized that the increased Itgb1 activity might contribute to the Sharpincpdm/cpdm dermatitis phenotype." (PMID 29040328, 2017). "Transgenic mice overexpressing integrin beta 1 (Itgb1) in the suprabasal layer of the epidermis (Tg(Itgb1)0869Fmw) exhibit epidermal hyperproliferation, perturbed keratinocyte differentiation and skin inflammation, which resembles the Sharpincpdm/cpdm phenotype." (PMID 29040328, 2017). "This study now demonstrates that Itgb1 inhibition in Sharpincpdm/cpdm mice significantly reduces epidermal proliferation and apoptosis, suggesting a modulatory role for integrins in the chronic proliferative dermatitis phenotype." (PMID 29040328, 2017). "Transgenic mice with suprabasal expression of Itgb1 displayed similar chronic proliferative dermatitis with deregulated keratinocyte proliferation and skin inflammation, although apoptosis was not significantly affected." (PMID 29040328, 2017).
dilated cardiomyopathy (2 papers, 2025). Cardiomyopathy which is characterized by dilation and contractile dysfunction of the left and right ventricles. "By combining volcano plot and GO analysis, we identified differentially expressed genes enriched in hypertrophic and dilated cardiomyopathy, including TTN, TPM3, CTTN, LAMA4, and ITGB1." (PMID 41214391, 2025).
endometrial cancer (2 papers, 2022 to 2024). Primary or metastatic malignant neoplasm involving the endometrium (mucous membrane that lines the endometrial cavity). "ITGB1 has been proposed as a direct target of repression by miR-183 in cervical and endometrial cancer, but in both tissues miR-183 acts as a tumor suppressor causing upregulation of the invasiveness promoter ITGB1." (PMID 35202085, 2022). "In endometrial cancer, ITGB1 has been identified as a surface marker for enriching endometrial cancer stem cells." (PMID 39239559, 2024).
glomerular diseases (2 papers, 2019 to 2024). "As we observed that CD9 expression in PEC correlated with PEC activation in experimental CGN and FSGS, and that CD9 depletion was associated with decreased ITGB1 levels, we analyzed CD9 expression in combination with CD44 and ITGB1 in human glomerulopathies." (PMID 31341160, 2019). "Such compelling evidence suggests that ITGB1 may have the potential to be a clinical marker for the prognosis of glomerular diseases, immune cell infiltration, and glomerular endothelial viability." (PMID 38674089, 2024). "We found that CD9 closely colocalized with ITGB1 during human extracapillary glomerulopathies such as ANCA-associated CGN and FSGS, but not in non-proliferative glomerulonephritides or in normal kidney." (PMID 31341160, 2019).
glomerulonephritis (2 papers, 2022). A renal disorder characterized by damage in the glomeruli. "Likewise, the dysregulation of pathways including glomerulonephritis and Genes controlling nephrogenesis (ITGB1), Nephrin/Neph1 signaling in the kidney podocyte (RAC1), and Nephrotic syndrome (MYH9) were also determined in this study due to the cytotoxicity effect of MWCNT." (PMID 35176998, 2022).
gout (2 papers, 2023 to 2026). A condition characterized by painful swelling of the joints, which is caused by deposition of urate crystals. "In gouty arthritis with cartilage damage, inflammation is enhanced by activating the ITGB1-dependent TLR2/4-NF-κB signaling pathway." (PMID 37941009, 2023).
inflammatory bowel disease (2 papers, 2020 to 2025). A spectrum of small and large bowel inflammatory diseases of unknown etiology. "Cluster 6 was characterized by the expression of the IFN-γ–induced genes Ifitm1, Ifitm2, and Ifitm3, which have been reported to be associated with inflammatory bowel diseases, alongside with the integrin Itgb1." (PMID 40924026, 2025).
Insulin resistance (2 papers, 2022 to 2025). Increased resistance towards insulin, that is, diminished effectiveness of insulin in reducing blood glucose levels. "On the other hand, the negative correlations between downregulated integrins ITGB1 and ITGA2B and the same glycemic control variables and others related to body composition and insulin resistance suggest a similar role in the inhibition of phosphorylation in these kinases." (PMID 35628588, 2022).
intracerebral hemorrhage (2 papers, 2021 to 2024). A cerebrovascular disorder characterized by bleeding into one or both cerebral hemispheres including the basal ganglia and the cerebral cortex. "This study explored the relationship between the expression of ITGB1 and ITGB3 in intracerebral hemorrhage (ICH) to analyze their functional and clinical relevance." (PMID 33641668, 2021).
laryngeal carcinoma (2 papers, 2021 to 2025). Carcinoma that arises from the laryngeal epithelium. "ISG15, ITGB1, PXN, SLC2A1 and ICAM1 are expected to become potential therapeutic targets for HPV-positive laryngeal cancer." (PMID 40821990, 2025). "Key genes like CDC42, PXN, ITGB1, PGK1, SLC2A1, ISG15 and ICAM1, affected by HPV, display distinct functional alterations and complex correlations in laryngeal cancer progression." (PMID 40821990, 2025). "PXN, ITGB1, ISG15, SLC2A1 and ICAM1 are regarded as potential therapeutic targets for HPV-positive laryngeal cancer." (PMID 40821990, 2025).
lung fibrosis (2 papers, 2024 to 2025). "Mechanistically, the downregulation of integrin ITGB1 may be a viable strategy for treating silica-induced pulmonary fibrosis." (PMID 39258668, 2024).
non-alcoholic steatohepatitis (2 papers, 2022 to 2023). "A recent study reported that ITGB1 mediated macrophage adhesion and promoted liver inflammation in murine nonalcoholic steatohepatitis." (PMID 35629036, 2022).
osteoporosis (2 papers, 2022 to 2024). A condition of reduced bone mass, with decreased cortical thickness and a decrease in the number and size of the trabeculae of cancellous bone (but normal chemical composition), resulting in increased fracture incidence. "In a parallel study on male subjects, DEPs were identified in monocyte membrane components and Integrin b1 (ITGB1) was found, shedding light on the possible contribution to osteoporosis." (PMID 39062769, 2024). "Collectively, these results revealed that miR-134-5p inhibits osteoclast differentiation of BMMs both in vivo and in vitro and that the miR-134-5p/Itgb1/MAPK pathway might be a potential target for osteoporosis therapy." (PMID 35691339, 2022). "Therefore miR-134-5p/Itgb1 may be a potential target in the regulation of bone remodeling and osteoporosis therapy." (PMID 35691339, 2022). "miR-134-5p/Itgb1 may be a potential target in regulating bone remodeling and osteoporosis therapy." (PMID 35691339, 2022).
ovarian tumor (2 papers, 2021 to 2025). "We examined the expressions of TIMP3, BRAF, and ITGB1 in ovarian tumor samples from both the LLU cohort and, subsequently, confirmed these findings using the TCGA database, stratified by race." (PMID 41294900, 2025). "It has been demonstrated that integrin β 1 (ITGB1), which is upregulated in OC, promotes ovarian tumor growth and progression and inhibits apoptosis by upregulating STAT1 expression." (PMID 33834023, 2021).
periodontitis (2 papers, 2023 to 2026). An acute or chronic inflammatory process that affects the tissues that surround and support the teeth. "In the Pg sample, we observed interactions between ADM and CALCRL, which is related to periodontitis; EDA and EDA2R, which is related to ectodermal development; and SPP1 and CD44 and SPP1 and (ITGA4+ITGB1), which promotes phosphoprotein secretion and regulates bone salinization." (PMID 37287452, 2023).